INS (insulin)
Diseases named in the same sentence as INS in open-access papers (continued):
Sharing a sentence is not in itself a finding about the gene and the disease.
MODY (continued). "This subtype of MODY is associated with a progressive decline in insulin secretion and heightened sensitivity to sulfonylureas, often allowing effective management without insulin, particularly in the early stages." (PMID 41367451, 2025). "Importantly, with the confirmation of MODY, affected individuals could be transitioned from daily, multiple insulin shots to an oral medication, which improved the glucose levels and positively impacted quality of life and clinical outcomes." (PMID 37353797, 2023). "Therefore, GLP-1 receptor agonist (GLP-1 RA) could be an effective therapy to consider in HNF4A-MODY patients with sulfonylureas failure or requiring discontinuing insulin." (PMID 37711893, 2023). "Besides, patients with different MODY subtypes might respond differently to oral drugs or insulin, making precise diagnosis important in guiding treatment selection." (PMID 34630320, 2021). "This suggests that FDA patients, rather than carrying mutations grossly affecting insulin synthesis and/or secretion (as in the case of MODY patients) are more likely to carry mutations involved in the fine tuning of insulin secretion or grossly affecting inulin sensitivity." (PMID 26287533, 2015). "Symptoms may be mild to more severe, but in all forms of MODY the problem is insulin deficiency due to a defect in pancreatic b-cell function rather than a defect in insulin action." (PMID 20587063, 2010). "Insulin treatment was interrupted, and the proband was reevaluated considering a possible diagnosis of T2DM or MODY." (PMID 39420905, 2024). "The higher levels of HbA1c (6.57% vs. 6.1%), and the higher percentage of patients requiring insulin therapy (25% vs. 2%) compared to the previously studied Italian patients with GCK/MODY, suggest that the mutation discovered could be responsible for a clinically worse form of GCK/MODY." (PMID 36835446, 2023). "The insulin requirements for pregnancy complicated with T1DM and MODY were higher than those for T2DM and GDM." (PMID 36339424, 2022). "Patients with HNF1B–MODY have been shown to be effectively treated with sulfonylurea, repaglinide, GLP-1 RA, and insulin in case reports." (PMID 36573710, 2022). "Among our 13 GCK-MODY patients, four were diagnosed in their childhood as having T1DM, three of them were treated with insulin therapy." (PMID 35592779, 2022). "Another type of MODY is MODY4 (PDX1), The PDX1 gene is involved in insulin gene transcription regulation." (PMID 34763692, 2021). "Up to 80% of MODY cases remain undetected or are misdiagnosed as T1DM or T2DM, resulting in incorrect treatment, including unjustified insulin therapy and its complications." (PMID 33477506, 2021). "These patients typically respond well to treatment with sulfonylurea, which increases insulin release from beta cells and is currently considered the treatment of choice for patients with HNF1A-MODY." (PMID 28593615, 2017). "Insulin is the first-line treatment option for this type of MODY since, unlike the MODY1 form, patients with MODY5 do not respond to oral antidiabetic treatments, such as sulfonylureas." (PMID 40901483, 2025). "Given that INS variants are associated with different mechanisms in the beta cell, causing impaired insulin processing and beta cell failure, it is not unusual that the clinical presentation of INS-MODY varies." (PMID 39717432, 2025). "For example, some MODY patients may retain sufficient endogenous insulin secretion to avoid transplantation altogether, or may respond to oral hypoglycemic agents, particularly sulfonylureas, in HNF1A-MODY." (PMID 40869931, 2025). "The actual prevalence of MODY is likely to be underestimated, as patients may be misclassified as T2DM due to insulin independence, or as T1DM due to young age and normal body mass index (BMI)." (PMID 39717432, 2025).
MODY (continued). "Mutations in KLF11 may hinder insulin secretion in pancreatic β-cells by inhibiting insulin promoter regulatory activity, consequently impairing insulin gene transcription in NDM and MODY." (PMID 38516000, 2024). "The correct molecular diagnosis in this case was critical to the patient, who could then be maintained on insulin therapy in addition to undergoing follow-up of her early-onset renal dysfunction and electrolyte disturbances characteristic of HNF1B MODY." (PMID 39420905, 2024). "In a retrospective analysis of pediatric MODY cases with beta-cell dysfunction at our outpatient clinic, all patients showed low insulin levels under 200 mU/l (data not shown)." (PMID 38550917, 2024). "Following these criteria, only five individuals had a diagnosis of MODY, since the majority of patients with MODY are known not to use insulin shortly after diagnosis." (PMID 36747290, 2023). "This figure compares T1DM and T2DM with MODY, attempting to mimic conditions in actual clinical practice where most individuals with MODY will not use insulin shortly after diagnosis." (PMID 36747290, 2023). "MODY classically presents in individuals with hyperglycemia before the age of 25 years, does not require insulin, and has evidence of autosomal dominant inheritance." (PMID 37016461, 2023). "This means that NIPT-GCK can facilitate a more tailored approach to pregnancy management in mothers with GCK-MODY, ensuring that insulin treatment is not started when the fetus has inherited the mutation." (PMID 37653058, 2023). "Where trial of non-insulin therapy is not undertaken and MODY is excluded our practice, in line with international guidance, is to keep the subtype under review and undertake serial C-peptide measurement." (PMID 37728732, 2023). "MODY is suspected in non-obese individuals with young-onset diabetes which does not require insulin treatment, lack islet autoantibodies and have persistent endogenous insulin." (PMID 34789499, 2022). "All subjects with T1DM and 18.6% of subjects with T2DM still required insulin administration after delivery, with a 26.9% (19.0, 46.0) and 36.7% (26.9, 52.6) decrease in total insulin dose, respectively, whereas subjects with GDM and MODY weaned off insulin completely." (PMID 36339424, 2022). "Insulin or oral hypoglycemic drugs are not effective in lowering the blood glucose levels or HbA1c levels in GCK-MODY patients, so there is no need to over-treat the patient (other than during pregnancy)." (PMID 34421822, 2021). "Insulin secretion, as assessed by the 60 min insulin-to-glucose ratio during an OGTT, was lower in HNF4α-MODY patients than in other MODY probands, indicating the presence of a more severe glucose-stimulated insulin secretory defect, although the comparison was made against only one subject." (PMID 34746319, 2021). "In MODY, secretion of C-peptide is intact, beta cell antibodies are absent and body mass index is normal; therefore, usually, there is no need for insulin treatment." (PMID 34681954, 2021). "We found that insulin suppression and glucagon release occur at a higher glucose levels in GCK-MODY than T2D and that there is an exaggerated epinephrine response to glucose lowering in GCK-MODY." (PMID 30146176, 2018). "GCK-MODY patients do not require treatment and do not respond to either oral agents or low-dose insulin." (PMID 28314945, 2017). "Perhaps the ‘troublemaker’ role of [GlnB22]-insulin during development of MODY does not result primarily from its limited biological potency." (PMID 25423173, 2014). "Clinical criteria for MODY include autosomal dominant inheritance, onset before age 30, correction of fasting hyperglycemia without insulin for at least two years post-diagnosis, and absence of ketosis." (PMID 19216786, 2009). "Many patients with RFX6-MODY do not appear to require insulin at diagnosis." (PMID 41636221, 2026).
MODY (continued). "In comparison to non-GCK-MODY patients, those with MODYX displayed increased 2-hour postload blood glucose levels (P = .01), △2-hour glucose (P = .019), a greater susceptibility to DK/DKA (P = .003), and more frequent usage of insulin injections (P = .027)." (PMID 39504571, 2025). "Features against a diagnosis of ABCC8-MODY are: (i) onset in adulthood; (ii) uncertain pathogenicity or likely benign nature of the ABCC8 mutations; (iii) good glycemic control without sulphonylurea or insulin." (PMID 38980630, 2024). "There are some subtypes of MODY that have little or no insulin therapy requirement for years." (PMID 36793123, 2023). "For the CEL, PDX1, INS, KCNJ11 and ABCC8 genes, MODY is caused only by specific variants resulting in dominant‐negative/gain of function effects; null variants in these genes do not cause MODY." (PMID 35445424, 2022). "In a recent study, among 16 patients with MODY who were offered treatment switch after genetic diagnosis, nine (six HNF1A, three KCNJ11) were stably switched from insulin to oral sulfonylurea but seven (three HNF4A, two ABCC8 and one each HNF1A and KCNJ11) had to restart insulin." (PMID 35618782, 2022). "MODY was originally defined as a clinical subgroup of familial diabetes that was diagnosed early (typically before 25 years of age) but despite this, this condition was not insulin dependent and showed autosomal dominant inheritance." (PMID 28314945, 2017). "It has not yet been determined whether [GlnB22]-insulin is secreted into the circulation in patients with MODY." (PMID 25423173, 2014). "Patients with MODY may be mistakenly treated with insulin despite not requiring it, as in our case." (PMID 40777711, 2025). "Maturity-onset diabetes of the young (MODY) is a monogenic form of diabetes characterized by early onset (usually under the age of 25 years), autosomal dominant inheritance and absence of insulin dependence during a variable period of time." (PMID 31968686, 2020). "Although GCK-MODY patients generally do not need any treatment, around 30% of the patients examined were receiving an unnecessary OAD or insulin therapy." (PMID 34440516, 2021). "In contrast, MODY generally does not require insulin treatment (especially GCK-MODY), although some subtypes (such as HNF1A-MODY) may necessitate insulin therapy as the condition progresses." (PMID 40520227, 2025). "In contrast with other MODY types, HNF1B-MODY patients do not respond to sulphonylurea, they usually require early insulin therapy and nephropathy management may also be necessary." (PMID 34440499, 2021). "Apart from antibodies, other laboratory findings that would increase the possibility of MODY are a relatively low HbA1c < 7.5% and the absence of DKA at the time of diagnosis, along with preserved C-peptide production, suggesting persistent beta cell function and insulin secretion." (PMID 39408828, 2024).
liver fibrosis (203 papers, 2007 to 2026). "This supports a potentially significant role of reduced insulin clearance as a risk factor for hepatic fibrosis associated with MetS." (PMID 39640841, 2024). "In a murine model of HFD-fed mice receiving chronic subcutaneous hippurate infusion, hippurate was associated with improved glycemic control, improved insulin secretion, reduced liver inflammation, and reduced liver fibrosis." (PMID 35848617, 2023). "The imbalance between production of tumor necrosis factor-alpha, interleukin-6, leptin, free fatty acids and adiponectin cause insulin resistance and inflammation that account for major pathophysiology of liver fibrosis in fatty liver." (PMID 35893894, 2022). "A longitudinal study of Japanese patients with NAFLD found that use of insulin and decrease in hemoglobin A1C levels were significantly associated with reductions in liver fibrosis." (PMID 35811319, 2022). "After viral clearance, adiponectin levels were directly associated with insulin sensitivity and decreased upon improved hepatic fibrosis." (PMID 34380427, 2021). "One study showed insulin treatment to be associated with advanced liver fibrosis, whereas another study associated insulin treatment with improvements in liver fibrosis." (PMID 33596938, 2021). "Liver fibrosis induced by a high fructose intake was associated with increased body weight, hunger-satiety system dysregulation, increased insulin concentration, dysregulated lipid metabolism, lipoperoxidation and inflammation." (PMID 33628193, 2021). "In the male offspring, these growth deficits persisted into adult life and associated with insulin hypersensitivity, increased markers of hepatic fibrosis and alterations in immune signaling." (PMID 30670059, 2019). "Thus, it is valuable to test the effects of the intracellular LPI accumulation caused by Aspg deficiency on the progression of MASH and hepatic fibrosis on the grounds of improved insulin sensitivity." (PMID 40760121, 2025). "Reducing the AGE–RAGE signaling, by controlling high glucose, sensitizing insulin function, avoiding overcooked foods, and oxidant supplement digestion, is a promising method in lowering the risk of DM and liver fibrosis in CHC patients, especially with increased AGEs and IR." (PMID 33195350, 2020). "The high starch intake led to a significant increase in postprandial blood glucose and insulin in serum of largemouth bass, promoting the synthesis and accumulation of large amounts of hepatic glycogen in the liver, leading to the loss of hepatocyte organelles and inducing liver fibrosis." (PMID 35677086, 2022). "Moreover, insulin levels happen to be associated with advanced liver fibrosis." (PMID 31807383, 2019). "While searching for clinical factors predicting outcomes from liver fibrosis, a key feature associated with the progression of cirrhosis and hepatocellular carcinoma, we found that tight glycemic control by diet or bolus-first insulin therapy ameliorated liver fibrosis." (PMID 23028442, 2012). "This sustained oxidative damage can impair organ function and contribute to the development of complications such as vascular damage, insulin resistance, and liver fibrosis." (PMID 40004164, 2025). "In terms of clinical implications, this study suggests that eGDR, a marker of insulin sensitivity, is inversely associated with both MASLD and liver fibrosis, highlighting its potential as a biomarker for early detection and risk stratification." (PMID 40520791, 2025). "Treatment with insulin or the STING agonist cGAMP alone significantly reduced PD-1 expression levels in NK cells from patients with advanced liver fibrosis." (PMID 40643462, 2025). "More interestingly, in pediatric NASH patients, pioglitazone (belonging to thiazolidinediones, an insulin sensitizer used in type 2 diabetic patients) demonstrated significantly greater efficacy than vitamin E in reversing liver fibrosis." (PMID 40142198, 2025).
liver fibrosis (continued). "The mechanisms by which adipose-derived hormones such as adiponectin and leptin signal to the liver, thereby regulating hepatic insulin sensitivity and liver fibrosis, are also essential." (PMID 40985048, 2025). "This study investigated the effects of geniposide (GP) on insulin sensitivity and hepatic fibrosis in a high-fat diet (HFD)-induced NASH model." (PMID 40869401, 2025). "For example, the interactive pathways in relation to the GR, the liver-X receptor (LXR) and the heterodimerisation partner RXR, hepatic fibrosis, cholestasis and insulin are influential." (PMID 39040675, 2024). "Quantitated liver cholesterol and triglycerides, serum insulin, and fasting blood sugar ameliorated their levels following vitamin D treatment in liver fibrosis mice." (PMID 39654627, 2024). "We found that EVs from young sedentary or acutely exercised mice, when delivered to aged mice, improve insulin sensitivity and distance traveled in the cage as well as delay aging‐induced liver fibrosis." (PMID 39269881, 2024). "It has been found that decreased hepatic glycogen synthesis in the liver is accompanied by a significant increase in all indicators of liver fibrosis, and rosiglitazone and insulin promote hepatic glycogen synthesis and inhibits hepatic glucose isomerization." (PMID 40626123, 2024). "The results of this feasibility study demonstrated the safety and potential therapeutic effect of orally delivered insulin formulations on liver fibrosis, fat accumulation, and inflammatory processes." (PMID 39131144, 2024). "The results of this feasibility study support the safety and potential therapeutic effect of orally delivered insulin on liver fibrosis, fat accumulation, and inflammatory processes (NIH Clinical Trials No. NCT04618744)." (PMID 39131144, 2024). "The effects of Pin1 on lipid accumulation, hepatic fibrosis, and oxidative stress were evaluated by biochemical analysis, glucose and insulin tolerance tests, histological analysis, IHC, RT-qPCR and Western blot assays." (PMID 38892011, 2024). "In the case of NAFLD, MD improves insulin sensitivity, reduces intrahepatic steatosis and mitigates hepatic fibrosis." (PMID 38817356, 2024). "In conclusion, the HCV core activates ISX‐relevant signals causing metabolic disturbance and immunosuppression, which further promote liver fibrosis and insulin resistance in vitro and in vivo." (PMID 37316966, 2023). "In nondiabetic patients with NAFLD, MET administration for 12 months ameliorated liver fibrosis, necrosis, inflammation, and lipid deposition, normalized the serum liver profile, and enhanced insulin sensitivity." (PMID 37894792, 2023). "The energy and calorie restriction diet helps control IR, hepatic insulin sensitivity, glucose tolerance, and liver fibrosis." (PMID 36142939, 2022). "Energy restriction and a low carbohydrate diet help to improve IR, hepatic insulin sensitivity, glucose tolerance, inflammation, hepatic lipogenesis, oxidative stress, and even liver fibrosis." (PMID 36142939, 2022). "GLP-1 can increase insulin release, decrease glucagon secretion, reduce hepatic steatosis, and improve hepatic fibrosis." (PMID 35770089, 2022). "Fer-1 plays a crucial role in weight control, glucose homeostasis and insulin sensitivity, as well as alleviating liver fibrosis and lowering hepatic TAG." (PMID 36588706, 2022). "In OB, interleukin-4 and interleukin-13 indicated via the IL-4R modulates adipose tissue lipolysis, insulin sensitivity, and liver fibrosis." (PMID 36314741, 2022). "In an animal model, CIH was found to activate the MAPK signaling pathways, which disturbed insulin secretion and led to pancreatic inflammation, liver fibrosis, and brain injury." (PMID 34185819, 2021). "Our study for the first-time reports that Rebaudioside A improves diet-induced NASH and hepatic fibrosis, possibly through improving ER stress, insulin sensitization, pancreatic autonomic innervation and microbiome composition." (PMID 32317687, 2020).